INS (insulin)
Diseases named in the same sentence as INS in open-access papers (continued):
Sharing a sentence is not in itself a finding about the gene and the disease.
Hyperinsulinemia (continued). "Long-term high-fat diets affect glucolipid metabolism, which further impairs the function of the liver and other metabolic organs, alters insulin and β-cell function, and ultimately leads to the development of elevated blood glucose, hyperinsulinemia, and other glucose metabolism disorders." (PMID 40806183, 2025). "However, sustained activation, as seen in over-nutrition or hyperinsulinemia, correlates with cell death and impaired glucose-stimulated insulin secretion." (PMID 39996055, 2025). "In response, the body produces more insulin, a phenomenon known as hyperinsulinemia." (PMID 40002645, 2025). "Therefore, to obtain normoglycemia, pancreatic β-cells secrete higher amounts of insulin, resulting in hyperinsulinemia." (PMID 39859258, 2025). "In response, pancreatic β-cells increase insulin concentration in a compensatory manner to maintain blood glucose homeostasis, leading to persistently elevated circulating insulin levels, a condition known as hyperinsulinemia." (PMID 41310487, 2025). "This reduction in FSH may result from metformin improving insulin sensitivity and reducing hyperinsulinemia, which affects gonadotropin secretion." (PMID 41411269, 2025). "Furthermore, the disruption of metabolic and inflammatory states can lead to reduced insulin tolerance and hyperinsulinemia, which then directly stimulate cell growth by binding on target cells like the pancreatic tissue." (PMID 40722646, 2025). "Moreover, the AQP-7 knockout mice showed hyperinsulinemia, decreased size and mass of beta cells, increased glucose-induced and basal insulin release, and increased triglycerides and glycerol contents." (PMID 40419958, 2025). "This could be due to early fetal hyperinsulinemia before the diagnosis of GDM because levels of fetal insulin in the amniotic fluid have been reported to be elevated already at week 16 in pregnancies in which women are later diagnosed with GDM." (PMID 38916475, 2025). "However, in insulin-resistant states, these processes become impaired, resulting in hyperinsulinemia and chronic hyperglycemia." (PMID 40281870, 2025). "We observed that its plasma levels negatively associated with BMI, insulin and hs- CRP, supporting its role in limiting body fat accumulation, protecting against hyperinsulinemia and myocardial infarction as well as its antioxidant and anti-inflammatory properties." (PMID 40485857, 2025). "Insulin-sensitive tissues become less responsive to insulin, and, to facilitate glucose uptake in peripheral tissues, beta cells in the pancreas compensate by increasing insulin production, a process known as "compensatory hyperinsulinemia"." (PMID 41472730, 2025). "Interestingly, levels of several hormonal peptides related to hyperinsulinemia, such as insulin, leptin, pancreatic peptide (PP), peptide YY (PYY), and gastric inhibitory polypeptide (GIP), were significantly upregulated." (PMID 39851552, 2025). "Calculating the insulin index in diets is considered to be useful in decreasing hyperinsulinemia." (PMID 40431370, 2025). "Finally, women with PCOS have a higher secretion of insulin (compared to healthy women of the same BMI) and lower hepatic insulin clearance, resulting in hyperinsulinemia." (PMID 40563843, 2025). "It seems that reduced insulin clearance is a significant contributor to hyperinsulinemia in PCOS." (PMID 40013621, 2025). "In the hyperglycemic state of GDM, the placenta secretes a variety of cytokines that enter the fetal circulation via the umbilical vein to induce pancreatic islet cell hyperplasia and hypertrophy in the fetus, leading to increased insulin secretion, or fetal hyperinsulinemia." (PMID 40797060, 2025). "The close association between excessive insulin secretion and metabolic dyshomeostasis has been shown in several studies, although the causal dynamics between hyperinsulinemia and metabolic dysfunction have hitherto lacked strong evidence." (PMID 40502600, 2025).
Hyperinsulinemia (continued). "This compensatory expansion could be a direct response to the improvement in insulin sensitivity induced by CS, reducing the demand for hyperinsulinemia and allowing structural recovery." (PMID 41471698, 2025). "This suggests that some of the reproductive and metabolic benefits of metformin may be partially due to its insulin-lowering effects in PCOS patients who have hyperinsulinemia." (PMID 40013621, 2025). "Biochemical analysis of serum insulin levels revealed hyperinsulinemia in DJ2−/− embryos." (PMID 41233317, 2025). "One advantage of introducing an insulin-centric approach is that available methods for assessing hyperinsulinemia and surrogate markers of IR could easily be incorporated into current management protocols." (PMID 40565766, 2025). "Decreasing insulin demand from beta-cells may be protective in people with T2D, as hyperinsulinemia overtime is followed by pancreatic beta-cell impairment and exogenous insulin dependence." (PMID 40410155, 2025). "However, the mechanisms differ: ob/ob mice develop hyperinsulinemia from excessive insulin production, whereas db/db mice display dysfunctional insulin secretion." (PMID 41226331, 2025). "Since elevated blood glucose is the most important stimulus for insulin secretion, this mechanism of action leads to the hypothesis that SGLT2i could be beneficial in treating horses with ID, by lowering hyperinsulinemia and subsequently preventing laminitis." (PMID 39113254, 2025). "Dysregulation of insulin, such as in the presence of hyperinsulinemia, may lead to the upregulation of the growth hormone receptor (GHR), consequently increasing hepatic production of IGF-I." (PMID 40431387, 2025). "In patients with T1DM, hyperinsulinemia may be misdiagnosed due to administration of exogenous insulin." (PMID 39859258, 2025). "In fact, hyperinsulinemia not only directly engages insulin and IGF-1R but also amplifies mitogenic signalling by boosting free IGF-1 availability, which activates IGF-1R, initiating signalling cascades such as PI3K, inhibiting apoptosis, and promoting protein synthesis." (PMID 40806650, 2025). "Thus, when there is full sensitivity to insulin-mediated lipogenesis and anti-lipolysis, hyperinsulinemia and intake of excess calories will promote development and maintenance of fat mass." (PMID 41009753, 2025). "Interestingly, it was also observed in this animal model that partial reduction in hyperinsulinemia improved insulin sensitivity and attenuated diet-induced abdominal tissue inflammation." (PMID 41009753, 2025). "A study suggests that BDNF may partially compensate for hyperinsulinemia by improving insulin sensitivity, thereby slowing the progression of T2DM." (PMID 40933306, 2025). "Since 2018, there has been an increasing interest in the human diabetes medication group sodium-dependent glucose transporter 2 (SGLT2)-inhibitors (SGLT2i) as a potential treatment for EMS, as this class of drugs have been shown to reduce hyperinsulinemia and increase insulin sensitivity in horses." (PMID 41408266, 2025). "Therefore, as the oral administration of insulin follows the same destination as the endogenously secreted insulin, peripheral hyperinsulinemia is avoided." (PMID 40427546, 2025). "For children with elevated HOMA-IR or hyperinsulinemia, targeted interventions to improve insulin sensitivity—such as dietary modifications, physical activity, or metformin—may enhance rhGH-induced growth." (PMID 41282298, 2025). "By alleviating hyperinsulinemia and aiding weight reduction, increased protein intake allows adipose tissue to shrink and become more insulin-responsive, thus lowering circulating fatty acids and toxic lipid byproducts that would otherwise strain the myocardium." (PMID 41470890, 2025).
Hyperinsulinemia (continued). "Given that insulin is a primary substrate of IDE, therapeutic enhancement of IDE activity could impair insulin clearance, worsening hyperinsulinemia and insulin resistance—especially in elderly or metabolically vulnerable individuals." (PMID 40724942, 2025). "If IR is not reversed through the implementation of lifestyle changes, basically nutrition improvement and physical exercise, pancreatic β-cell failure may occur due to the prolonged maintenance of hyperinsulinemia to compensate for poor insulin function." (PMID 41155548, 2025). "Even though there is no direct evidence that hyperinsulinemia itself adversely affects the liver, animal studies suggest that insulin is a direct cause of both hepatic steatosis and fibrosis." (PMID 41372973, 2025). "In contrast, in T1DM, persistent hyperinsulinemia due to exogenous insulin administration, combined with inflammatory responses and ovarian dysfunction, may contribute to the emergence of PCOS-like symptoms." (PMID 40429855, 2025). "BMEE demonstrated strong anti‐hyperinsulinemia by lowering the insulin levels." (PMID 39803222, 2025). "Consequently, measures that improve insulin sensitivity or reduce compensatory hyperinsulinemia are essential for mitigating the broad spectrum of IR-related cardiovascular complications." (PMID 40149704, 2025). "The observed hyperinsulinemia may reflect reduced insulin sensitivity in the peripheral metabolic tissues." (PMID 40564201, 2025). "However, in obese patients, as in the present case, early insulin induction increases weight gain, thereby worsening long-term glycemic management and increasing the risk of ASCVD due to hyperinsulinemia." (PMID 40226121, 2025). "Notably, a bidirectional regulatory relationship exists between leptin and insulin: insulin serves as a key regulator of leptin production, and chronic hyperinsulinemia sustains elevated circulating leptin levels." (PMID 41476920, 2025). "Restoring healthy gut microbiota may decrease hyperinsulinemia, enhance insulin sensitivity, and alleviate PCOS-related metabolic issues." (PMID 40234859, 2025). "Insulin therapy-induced exogenous hyperinsulinemia may contribute to the proliferation of colon and rectum epithelial cells." (PMID 40175445, 2025). "Notably, in humans, alterations in glucose metabolism—manifested by elevated blood glucose levels, reduced insulin sensitivity, and compensatory hyperinsulinemia—can be observed up to 13 years prior to the clinical diagnosis of T2DM." (PMID 41150735, 2025). "Furthermore, the body experiences elevated insulin levels under insulin-resistant conditions, exposing the liver to relative hyperinsulinemia." (PMID 40051521, 2025). "Initially, the cell responds appropriately by increasing insulin secretion (hyperinsulinism)." (PMID 40137942, 2025). "Notably, at later time points (18–20 weeks), the BTBRob/ob group and the SGLT2i + CR + BM-MSC group presented lower levels of insulin, contrasting with the hyperinsulinism observed in the other groups." (PMID 40394690, 2025). "Therefore, the objective of the study was to determine the effects of a commercial essential oil blend on hyperinsulinemia and insulin sensitivity in horses diagnosed with ID and evaluate the effect of essential oil treatment on the plasma metabolome." (PMID 39687851, 2024). "The WD lead to increased postprandial insulin production and may result in insulin oversecretion and hyperinsulinemia, promoting fat accumulation, inhibiting lipolysis, and causing increased appetite, hyperphagia, and weight gain." (PMID 38892561, 2024). "The mechanism is not fully understood but may be related to the reduction in insulin levels to improve hyperinsulinemia." (PMID 39201722, 2024). "Our results may also explain why hyperinsulinemia is a risk factor for BPH; high insulin levels can crossactivate the IGF1R." (PMID 37971878, 2024). "Insulin injections have been used as an experimental model to induce hyperinsulinemia." (PMID 39012663, 2024).
Hyperinsulinemia (continued). "This may be the cause of increased blood pressure during experimental sustained hyperinsulinemia as well as the development of hypertension in pregnant women during insulin therapy for gestational diabetes mellitus." (PMID 38323106, 2024). "The diagnosis of endogenous hyperinsulinemia relies on both the clinical presentation and a specific biochemical profile that demonstrates detectable serum insulin, detectable C-peptide with suppressed ketones, and suppressed free fatty acids in the setting of low plasma glucose." (PMID 39170749, 2024). "As previously discussed, hyperinsulinemia may act as a facilitator in cancer development, prompting numerous clinical studies to investigate whether therapies that elevate insulin levels contribute to tumorigenesis in DM patients." (PMID 39595655, 2024). "Hyperinsulinemia occurs firstly to compensate for the reduced sensitivity of cells to insulin." (PMID 39127712, 2024). "The downregulated insulin signaling in HFHSD+CUR-fed mice might result from the ameliorative effect of curcumin on HFHSD-induced hyperinsulinemia and the resulting signaling." (PMID 39056667, 2024). "Cortisol interferes with insulin signaling and promotes ID and hyperinsulinemia." (PMID 38396558, 2024). "Insulin-resistant states may hinder these physical processes, and consequently, hyperinsulinemia may encourage vascular constriction, potentially leading to vascular stiffening and even hypertension." (PMID 39309107, 2024). "Our ongoing investigation revealed that, compared to the Control group, the mice in the T2DM group had higher plasma insulin levels and a higher HOMA-IR ratio, and baicalein administration ameliorated the hyperinsulinemia and insulin homeostasis imbalance occurring in T2DM mice." (PMID 39456499, 2024). "There is growing evidence that aberrant insulin levels, as in the case of hyperinsulinemia, and insulin-mediated signaling may lead to cancer development and progression." (PMID 38392069, 2024). "Thus, in the pathological condition of hyperinsulinemia, insulin mainly stimulates HCC progression through interaction with INSR." (PMID 38952575, 2024). "Besides androgen, insulin and insulin-like growth factor-1 can contribute to hair follicle growth and also hyperinsulinemia, which suppress the sex hormone-binding globulin, a modulator of testosterone bioavailability." (PMID 39336541, 2024). "Hyperinsulinemia is also exacerbated by reduced hepatic insulin clearance." (PMID 38396558, 2024). "Indeed, experimental chronic hyperinsulinemia in healthy humans has been shown to significantly reduce insulin-stimulated glucose utilization while enhancing oxidative glucose disposal in skeletal muscle." (PMID 38435452, 2024). "In addition to the diabetogenic effect of GH outweighing the insulin-sensitizing effect of IGF-1, GH and IGF-1 act synergistically to increase insulin secretion, resulting in hyperinsulinemia." (PMID 39735646, 2024). "In support of the insulin hypersecretion hypothesis, chronic hyperinsulinemia itself is capable of decreasing the number of insulin receptors on the cell surface, thereby reducing tissue sensitivity to insulin." (PMID 38791525, 2024). "In individuals with hyperinsulinemia, elevated insulin levels reduce SHBG." (PMID 39290325, 2024). "In conclusion, the present randomized clinical trials indicated that the co-administration of (1000 mg/day) curcumin and DASH diet for 12 wk, can have positive effects on reducing insulin levels, improving IR, and leading to faster recovery of hyperinsulinemia." (PMID 39618714, 2024). "We found that insulin levels in the serum of mice treated with 0.2 or 0.08 mg/kg HF were significantly lower than in placebo-treated mice after 4 and 9 wk of treatment, revealing that HF reduced hyperinsulinemia." (PMID 39150520, 2024). "On the other hand, increased insulin secretion and/or decreased insulin clearance may lead to hyperinsulinemia during aging." (PMID 39734537, 2024).
Hyperinsulinemia (continued). "Furthermore, acute hyperinsulinemia during insulin clamp significantly decreases the urinary excretion of uric acid (UEUA)." (PMID 38579756, 2024). "As DNL in the liver is directly stimulated by insulin, subjects with hyperinsulinemia will accumulate liver fat more readily than others and so contribute to the development of metabolic (dysfunction)-associated fatty liver disease (MAFLD) (formerly called nonalcoholic fatty liver disease (NASH))." (PMID 38791525, 2024). "However, they were glucose intolerant and showed and higher plasmatic levels of C-peptide, which suggest the occurrence of previous or transient hyperinsulinemia, suggestive of reduced insulin sensitivity." (PMID 39445334, 2024). "In the case of T2D, insulin secretion may lose a portion of its negative regulatory mechanism, leading to hyperinsulinemia." (PMID 39950097, 2024). "Firstly, IR stimulates the secretion of insulin, and hyperinsulinemia leads to increased BMD." (PMID 38378872, 2024). "Insulin has been shown to inhibit the activity of aromatase in human trophoblasts, which may provide a mechanism for connecting hyperinsulinemia with placental androgen excess in women with PCOS." (PMID 38541997, 2024). "Moreover, erythrocyte samples were incubated with insulin to mimic the effects of IR-related hyperinsulinemia ex vivo." (PMID 39261864, 2024). "Ex-vivo islets from WC animals demonstrated hypersecretion of insulin in response to low but not high doses of glucose, suggesting that hyperinsulinemia was likely caused by elevated basal insulin secretion." (PMID 38961153, 2024). "The limited beta-cell capacity resulting in decreased insulin levels in the GDM dams could play a role in the protection against HF diet-induced weight gain, as hyperinsulinemia has been implicated as causal factor to diet-induced obesity." (PMID 38918525, 2024). "However, splanchnic palmitate uptake and VLDL-TG release are significantly suppressed during hyperinsulinemia, while the insulin-mediated suppression of splanchnic palmitate release and VLDL-TG uptake are less modified." (PMID 38901559, 2024). "Obese individuals secrete more insulin after consuming glucose, which leads to hyperinsulinemia." (PMID 38613048, 2024). "That is, T2DM is characterized in the first step by the fact that insulin action is impaired and pancreatic β-cells need to synthesize and secrete more insulin to compensate for this IR state, which could lead to hyperinsulinemia." (PMID 38952394, 2024). "In women with PCOS, polyphenols may play roles in disease prevention and treatment by reducing inflammation, enhancing insulin sensitivity, and managing compensatory hyperinsulinemia." (PMID 39459443, 2024). "Some studies suggested that long-term T2D might interfere with the molecular pathways of CRC, and that insulin sensitivity in T2D patients may lead to chronic compensatory hyperinsulinemia." (PMID 38483686, 2024). "This led to a compensatory increase in insulin secretion, resulting in hyperinsulinemia." (PMID 38732634, 2024). "HOMA-IR has been proven to be an excellent marker of hyperinsulinemia in the pediatric age: the higher predictive value of HOMA-IR is associated with a close relationship between basal and stimulated insulin level after OGTT, as clearly shown by several studies." (PMID 38920551, 2024). "Both the HFD and HFD + BJ groups displayed elevated postprandial insulin (p < 0.01; p < 0.001), which might reflect the attempt to overcome an increment in blood glucose (compensatory hyperinsulinemia), a feature of the prediabetic state." (PMID 38398840, 2024). "Increasing insulin production from the pancreatic beta cells to maintain normal glucose levels may lead to circulating hyperinsulinemia." (PMID 39513912, 2024).